METTL1 (methyltransferase 1, tRNA methylguanosine)
Description:
Catalytic component of METTL1-WDR4 methyltransferase complex that mediates the formation of N(7)-methylguanine in a subset of RNA species, such as tRNAs, mRNAs and microRNAs (miRNAs). Catalyzes the formation of N(7)- methylguanine at position 46 (m7G46) in a large subset of tRNAs that contain the 5'-RAGGU-3' motif within the variable loop. M7G46 interacts with C13-G22 in the D-loop to stabilize tRNA tertiary structure and protect tRNAs from decay. Also acts as a methyltransferase for a subset of internal N(7)-methylguanine in mRNAs. Internal N(7)-methylguanine methylation of mRNAs in response to stress promotes their relocalization to stress granules, thereby suppressing their translation. Also methylates a specific subset of miRNAs, such as let-7. N(7)- methylguanine methylation of let-7 miRNA promotes let-7 miRNA processing by disrupting an inhibitory secondary structure within the primary miRNA transcript (pri-miRNA). Acts as a regulator of embryonic stem cell self-renewal and differentiation (By similarity).
Synonyms: C12orf1; TRM8; TRMT8; YDL201w
Tractability: Small molecule: a structure with a bound ligand is known. PROTAC: ubiquitination databases record sites on it; its protein half-life has been measured.
Gene: Protein-coding gene on chromosome 12 (57,768,471 to 57,772,131, reverse strand). Ensembl gene ENSG00000037897.
Subcellular location: Nucleus
Subcellular location (Human Protein Atlas): Nucleoplasm
Pathways (Reactome):
Metabolism of RNA: tRNA modification in the nucleus and cytosol
Gene Ontology:
Molecular function: internal mRNA (guanine-N7-)-methyltransferase activity; protein binding; tRNA (guanine(46)-N7)-methyltransferase activity; tRNA binding
Biological process: cellular response to stress; RNA (guanine-N7)-methylation; tRNA (guanine-N7)-methylation; tRNA modification; tRNA stabilization; tRNA methylation
Cellular component: nucleoplasm; nucleus; tRNA (m7G46) methyltransferase complex; tRNA methyltransferase complex
Genetic constraint (gnomAD): Loss-of-function variants: 15 observed, 29.39 expected, observed/expected ratio (o/e) 0.51, 90% interval 0.34 to 0.79. The upper end of that interval is the gene's LOEUF score, 0.79, which puts it in group 3 of 6, group 1 being the genes least tolerant of losing a copy. Missense variants: 333 observed, 364.52 expected, observed/expected ratio (o/e) 0.91, 90% interval 0.83 to 1. Synonymous variants: 138 observed, 138.8 expected, observed/expected ratio (o/e) 0.99, 90% interval 0.87 to 1.14.
Homologues: Orthologues: chimpanzee METTL1 (99% identical), macaque METTL1 (99% identical), pig METTL1 (91% identical), dog METTL1 (90% identical), guinea pig METTL1 (89% identical), rabbit METTL1 (89% identical), rat Mettl1 (88% identical), mouse Mettl1 (88% identical), zebrafish mettl1 (66% identical), tropical clawed frog mettl1 (63% identical), Caenorhabditis elegans metl-1 (54% identical), Drosophila melanogaster CG4045 (54% identical).
Diseases named in the same sentence as METTL1 in open-access papers:
METTL1 is named in the same sentence as 118 diseases in open-access papers, as found by Europe PMC text mining. Sharing a sentence is not in itself a finding about the gene and the disease. The quoted sentences say what the papers report.
lung carcinoma (54 papers, 2017 to 2025). "Gain-of-function and mutational analyses further confirmed that METTL1 promotes lung cancer growth and invasion through regulation of tRNA m7G modifications." (PMID 41562049, 2025). "Furthermore, reintroduction of CCND3, a downstream effector of METTL1, partially restored the proliferation and metastatic capacity of METTL1‐deficient A549 lung cancer cells." (PMID 41208200, 2025). "Studies have shown that METTL1/WDR4 exhibits high expression levels in lung cancer tissues and that the loss of m7G tRNA modification impairs cell proliferation, colony formation, and cell invasiveness, ultimately reducing the tumorigenic potential of cancer cells both in vitro and in vivo." (PMID 38281298, 2024). "Studies have demonstrated that loss of METTL1/WDR4 impairs tRNA m7G modifications, markedly inhibiting lung cancer cell proliferation, colony formation, and invasion, as well as reducing tumorigenicity in vivo." (PMID 41562049, 2025). "In contrast to its broadly oncogenic activity in HCC, ICC, BCa and glioma, accumulating evidence indicates that m7G/METTL1 can exert tumour‐suppressive effects in lung cancer, colon cancer, and, in defined contexts, breast cancer." (PMID 41208200, 2025). "Aberrant RNA modifications have been increasingly recognized as critical contributors to lung cancer initiation and progression, with the m7G methyltransferase METTL1 emerging as a key regulatory factor." (PMID 41562049, 2025). "METTL1 enhances lung cancer growth and invasion by regulating m7G tRNA modifications, affecting mRNA translation of codon-biased transcripts, thus driving cancer progression." (PMID 40750708, 2025). "In lung cancer (LC), METTL1 disrupts the stability of its G‐quadruplex structure by methylating let‐7e pri‐miRNA, thereby enhancing miRNA processing and maturation, which in turn reduces the migratory capacity of cells." (PMID 41208200, 2025). "In lung cancer, METTL1/WDR4-mediated m7G tRNA modification functions as an oncogenic driver through changing translational efficiency of m7G tRNA codon-enriched mRNAs." (PMID 40809384, 2025). "METTL1 also regulates MiR‐149‐3p axis through m7G methylation and let‐7e miRNA/HMGA2 axis to inhibit lung cancer cell proliferation and migration, causing LC progression." (PMID 41208200, 2025). "METTL1 was shown to methylate let‐7e primary miRNA precursors in lung cancer cells, leading to the maturation of miRNA processing." (PMID 41208200, 2025). "In lung cancer, components of the tRNA m7G methyltransferase complex, METTL1 and WDR4, are significantly upregulated and correlate with poor patient prognosis." (PMID 41562049, 2025). "METTL1 knockdown hampers tRNA modifications and lowers mRNA translation, consequently diminishing the invasion and carcinogenicity of lung cancer cells." (PMID 38706740, 2024). "Results from GEPIA suggested that METTL1 is upregulated in lung cancer, including LUAD and squamous cell carcinoma, comparing to the pericarcinomatous tissue (p < 0.05)." (PMID 38967523, 2024). "In lung cancer cells,METTL1 knockdown in A549 cells and Caco-2 cells resulted in significantly enriched m7G-containing miRNAs, including miR-92(3p), let-7(5p), and miR-125(5p)." (PMID 36810782, 2023). "This shows that METTL1 affects lung cancer both positively and negatively, but ultimately exhibits cancer-promoting effects through a complex mechanism." (PMID 37710294, 2023). "For example, overactive METTL1 can promote the methylation and maturation of m7G in let-7 miRNA, a tumor suppressor miRNA, thereby inhibiting the metastasis of lung cancer cells." (PMID 37654606, 2023). "Further investigation unveiled that METTL1/WDR4 accelerated lung cancer cell proliferation and migration by enhancing tRNA m7G modification and oncogenic mRNA translation, particularly CCND3 and CCNE1, the cell-cycle regulators." (PMID 36733406, 2023).
lung carcinoma (continued). "In lung cancer, METTL1 downregulates the production of oncogenes through miRNAs while simultaneously promoting tumor cell proliferation through the AKT/mTORC1 signaling pathway." (PMID 37710294, 2023). "In lung cancer, METTL1 mediated m7G tRNA modification and m7G tRNA decoded codon usage, enhances the translation of mRNA and in turn promotes lung cancer progression." (PMID 36923941, 2023). "And m7G tRNA modifications and m7G codon usage mediated by promote METTL1/WDR4 oncogenic mRNA translation to facilitate lung cancer progression." (PMID 36396627, 2022). "Highly expressed m7G-related genes were found in the lung cancer patient tissues, and METTL1 promoted the development and metastasis of lung cancer through the modification of tRNA." (PMID 36003341, 2022). "The elevation of METTL1 and WDR4 were reported to be related with worse prognosis of human lung cancer and intrahepatic cholangiocarcinoma negatively associated with patient." (PMID 36118897, 2022). "METTL1/WDR4 also catalyzed m7G modification at let-7 miRNA to promoted the tumor suppressor miRNA processing from primary to precursor miRNA in lung cancer." (PMID 36396627, 2022). "miRNA m7G modification mediated by METTL1 promotes lung cancer occurrence and inhibits cancer metastasis; however, the researchers did not rule out the effect of METTL1 on mRNA." (PMID 36199792, 2022). "METTL1, as one of the key tRNA-modifying enzymes, has been extensively reported to promote cancer development by mediating tRNA m7G modifications in lung cancer, ICC, HCC, and bladder cancer." (PMID 35785179, 2022). "Their findings uncovered the oncogenic role of METTL1/WDR4-mediated m7G tRNA modification in lung cancer." (PMID 36353111, 2022). "Methyltransferase like 1 (METTL1) enzyme has been reported as a potential writer in lung cancer and colon cancer cells." (PMID 33430133, 2021). "Methyltransferase METTL1 is required for m7G modification of miRNAs, their efficient processing, and the inhibition of lung cancer cell migration." (PMID 31031083, 2019). "MiR-149-3p served as a tumor suppressor in multiple cancers, and upregulated METTL1 increased miR-149-3p levels in lung cancer cells in a m7G dependent manner." (PMID 31866582, 2019). "In case of copy number variation, we found METTL1 to be amplified and over-expressed in other cancers including lung cancer." (PMID 28035070, 2017). "For example, METTL1 can act as a tumor suppressor in lung cancer by enhancing miRNA processing." (PMID 41446042, 2025). "However, overexpression of METTL1/WDR4 is also indicative of poor prognosis in lung cancer patients." (PMID 38706740, 2024). "In contrast, METTL1/WDR4-mediated m7G-modified microRNAs suppressed the progression of lung cancer." (PMID 37283791, 2023). "The upregulated expression levels of METTL1 and/or WDR4 and their association with prognosis were observed in multiple types of cancer, including lung cancer, esophageal squamous cell carcinoma (ESCC), intrahepatic cholangiocarcinoma (ICC), hepatocellular carcinoma (HCC), and glioma." (PMID 36733406, 2023). "Recent data have demonstrated that METTL1 could methylate let-7e miRNA precursor in lung cancer cells, consequently inhibiting the progression and invasion of lung cancer." (PMID 37371664, 2023). "In tumors including nasopharyngeal carcinoma, lung cancer, hepatocellular carcinoma, and squamous cell carcinoma of the head and neck, METTL1 is able to mediate tRNA m7G modifications that regulate the translation process and ultimately lead to tumor progression." (PMID 37599359, 2023). "METTL1 was a methyltransferase catalyzing m7G modification of tRNAs, and METTL1-mediated tRNA modification drives oncogenic transformation and promotes lung cancer progression." (PMID 36761423, 2022). "Additionally, in lung cancer, m7G tRNA modifications mediated by METTL1/WDR4 were found to play a crucial role in regulation of mRNA translation process and cancer progression." (PMID 36545327, 2022).
lung carcinoma (continued). "METTL1 accelerated let-7 miRNA processing, thereby inhibiting lung cancer cell migration." (PMID 35986847, 2022). "Although studies of METTL1 have been limited, overexpression of METTL1 could drive tumor progression which was reported in hepatocellular carcinoma, colon cancer, intrahepatic cholangiocarcinoma, and lung cancer." (PMID 35432338, 2022). "Ma's group found that both WDR4 and METTL1 were significantly upregulated in human lung cancer." (PMID 36186903, 2022). "METTL1 mainly regulates the modification of N7-methylguanosine (m7G) and plays an important role in the progression of tumors, such as colon cancer, liver cancer, and lung cancer 50-52." (PMID 33854615, 2021). "The downregulation of mature let-7e would cause overexpression of its target genes, such as the high mobility group AT-hook 2 (HMGA2), RAS and MYC driver genes of metastasis, thus making METTL1-mediated m7G editing important for inhibiting lung cancer cell migration." (PMID 34638933, 2021). "METTL1 was shown to methylate let-7e primary miRNA precursor (pri-miRNA) in lung cancer cells." (PMID 34638933, 2021). "It is evidenced that the m7G methylation of let-7 miRNA induced by methyltransferase like 1 (METTL1) could regulate the process of lung cancer." (PMID 32806547, 2020). "The WD repeat domain 4 (WDR4) complex and methyltransferase-like 1 (METTL1) complex either enhanced or impeded the processes of several malignancies, including squamous cell carcinoma and lung cancer." (PMID 40658715, 2025). "Elevated levels of METTL1 correlates with poor prognosis of various cancers, including bladder cancer (BLCA), hepatocellular carcinoma (HCC), lung cancer, colon cancer, liver cancer, and glioma." (PMID 40809384, 2025). "The METTL1/WDR4 complex is abnormally overexpressed in various tumor types, including lung cancer, ESCC, and head and neck squamous cell carcinoma (HNSCC)." (PMID 41446042, 2025). "It had been demonstrated experimentally that METTL1/WDR4 can regulate the development of cancer through tRNA modification of m7G methylation in intrahepatic cholangiocarcinoma, lung cancer and nasopharyngeal carcinoma." (PMID 38987843, 2024). "Through m7G alteration of tRNA or miRNA, the METTL1/WDR4 complex influences the course of several malignancies, such as liver cancer, lung cancer, and colon cancer." (PMID 36816047, 2023). "METTL1 and WDR4 were found to be up-regulated in lung cancer tissues which promoted tumor cell proliferation and migration." (PMID 37710294, 2023). "The expression levels of METTL1 and WDR4 are also significantly higher in lung cancer than in normal lung tissue, and this is closely related to poor prognosis." (PMID 36333719, 2022). "The m7G methyltransferase METTL1 and WDR4 complex is significantly elevated in lung cancer, which can promote lung cancer cell growth and invasion and negatively correlate with patient prognosis." (PMID 36553648, 2022). "Another study showed high METTL1 and WDR4 expression levels in lung cancer, facilitating m7G tRNA modification, altering mRNA translation, and boosting lung cancer development and invasion." (PMID 35982949, 2022). "WDR4 combined with METTL1 as m7G methyltransferase complex components, and it had been reported that depletion of METTL1 and WDR4 resulted in decreased lung cancer cell progression." (PMID 36761423, 2022). "In contrast, the tumor-promoting role of METTL1 was reported in hepatocellular carcinoma (HCC), lung cancer, and head and neck squamous cell carcinoma." (PMID 35986847, 2022). "METTL1 promotes cell proliferation and autophagy through the AKT/mTORC1 signaling axis to promote lung cancer progression." (PMID 36333719, 2022). "It is worthwhile to determine crosstalk and functional roles between METTL1, CTU2, and XPOT in human cancer, notably lung cancer." (PMID 34285249, 2021). "Furthermore, in lung cancer, METTL1/WDR4 deletion leads to impaired tRNA m7G modification, which affects lung cancer cell proliferation and tumourigenesis." (PMID 38572667, 2024).
lung carcinoma (continued). "METTL1 or WDR4 expression dysregulation has been detected in many tumors, including bladder cancer, head and neck squamous cell carcinoma, hepatocellular carcinoma, and lung cancer 27-30." (PMID 37283791, 2023). "Moreover, METTL1 or WDR4 depletion inhibited proliferation and invasion, as well as in vivo tumor growth of lung cancer cells." (PMID 36353111, 2022). "In lung cancer cases, METTL1 and WDR4 were both remarkably raised and had a negative correlation with invalids’ prognosis." (PMID 36118897, 2022). "Additionally, we performed qRT-PCR assays, and revealed that METTL1 was highly expressed in several cancer lines, such as the breast cancer line MCF7 and the lung cancer line A549." (PMID 34285249, 2021). "In addition, METTL1‐mediated m7G modification is regulated by mature let‐7e, and knockdown of it leads to high expression of its target genes HMGA2 and MYC metastasis driver, which inhibits lung cancer cell migration and invasion." (PMID 38572667, 2024). "Moreover, the expression levels of METTL1 and WDR4 were also significantly upregulated in lung cancer tissues, and METTL1-mediated m7G tRNA modifications can regulate the mRNA translation to promote the proliferation and invasion of lung cancer, revealing m7G modification as a key oncogenic factor." (PMID 37158958, 2023). "METTL1 may have both positive and negative effects on the emergence of lung cancer." (PMID 37710294, 2023). "Impaired m7G tRNA modification in the absence of METTL1/WDR4 results in decreased proliferation, colony formation, cell invasion, and tumorigenicity of lung cancer cells." (PMID 36553648, 2022).